MIR6773 (microRNA 6773)
Synonyms: hsa-mir-6773
Gene: MicroRNA gene on chromosome 16 (68,233,426 to 68,233,499, reverse strand). Ensembl gene ENSG00000284259.
Homologues: Orthologues: chimpanzee MIR6773 (100% identical).